CXCL14 (C-X-C motif chemokine ligand 14)
Diseases named in the same sentence as CXCL14 in open-access papers (continued):
Sharing a sentence is not in itself a finding about the gene and the disease.
prostate carcinoma (30 papers, 2012 to 2025). A carcinoma that arises from epithelial cells of the prostate gland. "Next, we examined the association of EGFR and YB-1 as well as CXCL14 expression with clinical and pathological characteristics in human prostate cancer tissues using IHC." (PMID 34696665, 2021). "CXCL14 is a chemokine with a pro-tumor role in breast and prostate carcinoma, where it is secreted by cancer associated fibroblasts, and contributes to tumor growth and invasion." (PMID 31117166, 2019). "This approach, which is novel to the field of prostate cancer to the best of our knowledge, facilitated the identification of three novel aggressive prostate cancer susceptibility genes: CXCL14, ITGAX, and LPCAT2." (PMID 25411967, 2014). "For example, restored CXCL14 expression in HPV-positive oropharyngeal carcinoma is associated with better survival in immunocompetent syngeneic mice but CXCL14-producing CAFs promoted tumor growth in a prostate cancer model." (PMID 37076857, 2023). "CXCL14, on the other hand, was downregulated in prostate cancer, and was negatively associated with YB-1, thus it may be a valuable prognostic role for predicting future disease states and reflecting cancer cell aggressiveness." (PMID 34696665, 2021). "Additionally, a linkage study demonstrated that CXCL14 resides in a risk locus for aggressive prostate cancer in the 5q31 region, and higher levels of this gene have been observed in tumors with a higher Gleason score." (PMID 25411967, 2014). "Research demonstrates that exosomes secreted by prostate cancer cells are enriched with the chemokine CXCL14." (PMID 41357241, 2025). "For instance, a previous study demonstrated that the fibroblast‐derived factor CXCL14 promoted the proliferation and migration of prostate cancer cells in vitro, as well as angiogenesis in vivo." (PMID 40162549, 2025). "By modulating autophagic activity in ST2 cells, lncAY927529 influences the secretion of the chemokine CXCL14, which in turn promotes the proliferation and invasion of neighboring prostate cancer cells via a paracrine mechanism." (PMID 41357241, 2025). "Exosomal CXCL14 contributed to M2 macrophage polarization through NF-kB signaling pathway to promote the progression of prostate cancer." (PMID 38232115, 2024). "Pancreatic and prostate cancers show increased CXCL14 expression, while other cancer types, including cancers of breast, kidneys, and cervix, show downregulated CXCL14 expression." (PMID 35330734, 2022). "In prostate cancer, CXCL14-producing fibroblasts can also enhance proliferation and migration in vitro and angiogenesis in vivo." (PMID 35769715, 2022). "With the hope of being able to aid the development of novel therapeutics, this study aimed at characterizing the EGF regulation in YB-1 and CXCL14 expression and their relevant kinase pathways in prostate cancer cells and tissues." (PMID 34696665, 2021). "Our study also showed that EGF regulate CXCL14 transcription, and that CXCL14 is inversely correlated with YB-1 in prostate cancer cells, suggesting a possible mechanism of YB-1 regulation in the cell cycle and in apoptosis in prostate cancer." (PMID 34696665, 2021). "Next, we analyzed associations between the survival time of prostate cancer patients and levels of YB-1, EGFR and CXCL14 expression." (PMID 34696665, 2021). "Our IHC study illustrated that YB-1 and EGFR are significantly expressed in prostate cancer tissues with a high Gleason score, while CXCL14 was lowly expressed." (PMID 34696665, 2021). "The possible links between EGF-mediated YB-1 and CXCL14 as well as the functions of critical kinase pathways in the progression of prostate cancer have remained unexplored." (PMID 34696665, 2021). "The fundamental regulatory mechanism of YB-1 and CXCL14 in prostate cancer needs to be further explored." (PMID 34696665, 2021). "Positive and negative regulation of YB-1 and CXCL14 was observed after EGF treatment in prostate cancer cells, respectively." (PMID 34696665, 2021).
prostate carcinoma (continued). "CXCL14 expression is known to upregulate in prostate cancer and positively correlate with its tumor progression." (PMID 33298014, 2020). "For example, CXCL14 mRNA levels are significantly up-regulated in localized prostate cancer, and CXCL14 expression levels are positively correlated with Gleason scores in prostate cancer." (PMID 31014014, 2019). "In spite of these data, overexpression of CXCL14 in prostate cancer (LAPC4) cells by introducing mouse or human CXCL14 expression vectors suppresses tumor growth in vivo compared with the growth of control vector-transfected tumor cells." (PMID 31014014, 2019). "In line with our findings, CXCL14 has been previously reported to promote motility and invasion of breast and prostate cancer cells and bone metastasis of lung cancer cells." (PMID 28003019, 2016). "Previous studies have demonstrated that CXCL14 was epigenetically silenced in some cancers such as lung adenocarcinoma and prostate cancer." (PMID 25760073, 2015). "In summary, we have identified CXCL14, ITGAX and, LPCAT2 as novel susceptibility genes for aggressive prostate cancer development." (PMID 25411967, 2014). "Second, three of these five genes (CXCL14, ITGAX, and LPCAT2) harbored polymorphisms associated with aggressive disease development in a human GWAS cohort consisting of 1,172 prostate cancer patients." (PMID 25411967, 2014). "CXCL14 is important in the progression of many malignancies, including colorectal cancer, and is epigenetically silenced in lung and prostate cancer." (PMID 24944583, 2014). "As regards to the angiostatic role of CXCL14, in a model of human prostate cancer transfected with CXCL14, 43% reduction tumor growth as compared to controls was found." (PMID 24971349, 2014). "Concomitantly, over-expression of CXCL14 in fibroblasts stimulates tumor angiogenesis and growth of prostate cancer cells through activation of NOS1-derived nitric oxide signaling pathways." (PMID 25411967, 2014). "In prostate cancer, CXCL14/BRAK mRNA is significantly upregulated in localized prostate cancer and its level positively correlates with the Gleason score." (PMID 23762619, 2012). "Furthermore, CXCL14 was found to be highly expressed in subtype 1 and studies suggested that this chemokine is responsible for better prognosis in prostate cancer which opens up a possibility for this chemokine to become an effective marker for bladder cancer." (PMID 38172584, 2024). "Additionally, CAF overexpresses and secretes CXCL14 in breast and prostate cancer and promotes tumor growth and invasion compared to normal stromal cells 37-39." (PMID 37056937, 2023). "Furthermore, CXCL14 is overexpressed in the stromata of the breast and pancreas and prostate cancer 9-11." (PMID 37056937, 2023). "In addition, the human CXCL14 protein also had similar effects in other cancer cells, such as cervical cancer, esophageal cancer and prostate cancer." (PMID 37835641, 2023). "In prostate cancer, CXCL14-producing fibroblasts have enhanced pro-tumoral effects." (PMID 37091868, 2023). "YB-1 and CXCL14 were inversely correlated in prostate cancer." (PMID 34696665, 2021). "YB-1 and CXCL14 were inversely correlated in prostate cancer cells and tissues." (PMID 34696665, 2021). "Furthermore, YB-1 silencing induces G1 arrest and apoptosis, while knockdown of CXCL14 facilitates cell growth and inhibits apoptosis in prostate cancer cells." (PMID 34696665, 2021). "A high CXCL14 expression exhibited a longer survival time in prostate cancer patients." (PMID 34696665, 2021). "There is evidence for epigenetic regulation of CXCL14 in prostate cancer cells." (PMID 31366318, 2019). "However, interesting enough, overexpression of normal CXCL14/BRAK in prostate cancer cells by introducing mouse or human CXCL14/BRAK expression vectors retards tumor growth in vivo compared with the growth of control vector-transfected tumor cells." (PMID 23762619, 2012).
prostate carcinoma (continued). "In the process of characterizing the subset of CAFs with CXCL14 overexpression, we noticed that they were mainly clustered in the iCAF and naïve-CAF subsets, which is also consistent with reports of prostate cancer." (PMID 40898244, 2025). "In prostate cancer, researchers find that CAFs secretes CXCL12 and CXCL14 to promote macrophage M2 polarization." (PMID 38827236, 2024). "In prostate cancer, CAFs can recruit and activate monocytes to generate M2 macrophages via CXCL12 and CXCL14." (PMID 36418470, 2023). "Here we examined the correlation between YB-1 and CXCL14, and the ERK/AKT/mTOR pathways in prostate cancer." (PMID 34696665, 2021). "In conclusion, our data reveal the functional relationship between YB-1 and CXCL14 in EGF mediated ERK signaling, and YB-1 expression is a significant prognostic marker to predict prostate cancer." (PMID 34696665, 2021). "Here, our IHC data revealed a low-level expression of CXCL14 and a high EGFR expression in prostate cancer tissues." (PMID 34696665, 2021). "While the overall survival of EGFR and CXCL14 expression and the Gleason score of prostate cancer patients is without significant difference." (PMID 34696665, 2021). "CXCL14, as a fibroblast autocrine growth factor can act as a prostate cancer stimulator and high CXCL14 gene expression in -CD82 cells may indicate a possible link between CXCL14 and CD82 in the tumorigenesis of prostate cancer." (PMID 33298014, 2020). "The significantly upregulated genes in -CD82 cells such as CXCL14 and FGF13 could potentially serve as biomarkers or therapeutic targets for diagnosis and treatment of prostate cancer." (PMID 33298014, 2020). "NIH-CXCL14 cells, but not recombinant CXCL14, enhance the in vitro proliferation and migration of prostate cancer cells and promote in vivo angiogenesis in the NIH-CXCL14 system." (PMID 31014014, 2019). "While previously discussed in another work, in breast and prostate cancer, focusing on CXCL14 and its secretion by fibroblasts suggest that CXCL14 can be involved in CAF-mediated PDAC resistance mechanisms; more work is needed to fully understand CXCL14’s diverse role in the PDAC TME." (PMID 38339310, 2024). "Furthermore, the chemokine C-X-C motif ligand 14 (CXCL14) exerts paradoxical roles on tumorigenesis, since it suppresses the in vivo growth of lung and head-and-neck carcinoma cells while promoting invasion of breast and prostate cancer cells." (PMID 33255335, 2020). "However, the role of CXCL14 in prostate cancer (PC) has not been fully investigated." (PMID 35669852, 2022). "Stromal CXCL14, but not tumor CXCL14, is reported to promote progression, and CAF-secreted CXCL14 has been reported to promote tumor growth and invasion of breast and prostate cancer cells." (PMID 40898244, 2025).
colorectal cancer (24 papers, 2013 to 2025). A primary or metastatic malignant neoplasm that affects the colon or rectum. "HyperCAFs also express the CXCL14, elevated CXCL14 levels in CAFs of clinical specimens are also associated with higher risks for disease recurrence and worse overall survival time in colorectal cancer." (PMID 37719863, 2023). "Instead, the associations between increasing expression levels of CXCL14 protein and better patient outcomes have been verified in breast and colorectal cancers." (PMID 34696665, 2021). "The results showed only CXCL14 remained a prognostic factor in disease-free survival of early-stage colorectal carcinoma patients (risk ratio, 2.92; 95% CI, 1.15-7.40; P = 0.024)." (PMID 23294544, 2013). "Till now, there has been little data suggesting the association between CXCL14 and colorectal carcinoma." (PMID 23294544, 2013). "Our results showed that elevated CXCL14 expression in primary colorectal cancers was associated with poor disease-free survival and overall survival, indicating CXCL14 might be used as a potential prognostic marker for CRC patients." (PMID 23294544, 2013). "Results showed CXCL14 expression could be used as a prognostic factor in overall survival of colorectal carcinoma patients (risk ratio, 3.087; 95% CI, 1.866-5.107; P < 0.001)." (PMID 23294544, 2013). "In addition, NK cell depletion increases the risk of colorectal cancer in Cxcl14 transgenic mice." (PMID 27143385, 2016). "The concentrations of other parameters (CCL11, CCL26, CXCL14 and CA 19-9) were comparable to or even lower in the sera of patients with colorectal cancer compared to the group of healthy volunteers." (PMID 37240636, 2023). "CXCL14 is upregulated in glioblastoma, osteosarcoma, ovarian cancer, thyroid carcinoma, and endometrioid carcinoma, while downregulated in melanoma, colorectal cancer, and hepatocellular carcinoma." (PMID 36721112, 2023). "The expression of CXCL14 in colorectal cancer tissues was correlated with TNM stage and poor prognosis." (PMID 38075694, 2023). "In the case of CXCL14, we have observed a statistically lower concentration of this parameter in the serum of colorectal cancer patients when compared to healthy volunteers." (PMID 37848726, 2023). "The relationship between CXCL14 gene silencing and promoter hypermethylation was revealed through the colorectal carcinoma methylation database." (PMID 38003215, 2023). "The results suggest that CXCL14 is a tumor suppressor gene in colorectal carcinoma which is activated first and then silenced during the process of tumor occurrence and deterioration." (PMID 38003215, 2023). "Herein, we reported experimental evidence for ROS-induced cell cycle progression and the epithelial to mesenchymal transition (EMT) process via CXCL14/pERK pathway in colorectal cancer cells." (PMID 34744744, 2021). "It has been reported that chemokine CXCL14 expression correlates with the prognosis of colorectal cancer after resection." (PMID 33733587, 2021). "We found that CXCL14 modulated ROS-induced cell proliferation and motility in colorectal cancer cells, suggesting an oncogenic role of CXCL14 in CRC, which was consistent with our previous studies." (PMID 34744744, 2021). "The seven significant colorectal cancer associated genes shortlisted from the differentially expressed genes were CALD1, CTNNB1, CXCL14, PTCH1, CXCL8, TNFAIP3, and NNMT after mapping with PubMed, OMIM, MeSH, and PMC databases." (PMID 32523911, 2020). "CXCL14 expression is epigenetically regulated by promoter hypermethylation in colorectal cancer cells." (PMID 27143385, 2016). "CXCL14 is also known to control colorectal cancer by inhibiting migration and invasion by suppressing NF-κB signaling." (PMID 25814785, 2015). "Apart from gastric cancer CXCL14 is silenced in colorectal cancer by frequent methylation of the promoter region." (PMID 25814785, 2015).
colorectal cancer (continued). "This study was therefore designed to investigate the expression and clinical significance of CXCL14 in colorectal cancer." (PMID 23294544, 2013). "An overall survival analysis of 135 colorectal cancer patients indicated that the level of CXCL14 expression was inversely correlated with survival time of the patients after surgery." (PMID 23294544, 2013). "In vitro studies further validated the role of CXCL14 in colorectal cancer cell migration and invasion." (PMID 23294544, 2013). "Collectively, these data identified previously unrecognized growth-stimulatory effects of CXCL14 on colorectal cancer cells." (PMID 23294544, 2013). "These analyses indicated that up-regulation of CXCL14 in colorectal cancer cells was correlated with tumor progression." (PMID 23294544, 2013). "The observation that there was good correlation between CXCL14 levels and Ki67 in human colorectal cancer suggested that CXCL14 was involved in human colorectal cancer cell proliferation." (PMID 23294544, 2013). "In the present study, immunohistochemical analyses and a number of in vitro studies were performed to validate the aggressive role of CXCL14 in colorectal cancer progression." (PMID 23294544, 2013). "To explore the effect of CXCL14 on colorectal cancer cell proliferation, we investigated the expression levels of CXCL14 mRNA and protein in four different colorectal cancer cell lines: HCT116, SW620, RKO and LoVo." (PMID 23294544, 2013). "In summary, these results provide the first definitive immunohistochemical evidence that CXCL14 expression is up-regulated in colorectal cancer." (PMID 23294544, 2013). "The effect of CXCL14 on colorectal carcinoma cell proliferation was measured by MTT assay, BrdU incorporation assay and colony formation assay." (PMID 23294544, 2013). "Patients with early-stage (I/II) colorectal carcinoma were divided into low-CXCL14-expressing tumor group (n = 69) and high-CXCL14-expressing tumor group (n = 22)." (PMID 23294544, 2013). "Functional studies demonstrated that enforced expression of CXCL14 in SW620 colorectal carcinoma cells resulted in more aggressive phenotypes." (PMID 23294544, 2013). "The impact of CXCL14 on migration and invasion of colorectal carcinoma cells was determined by transwell assay and Matrigel invasion assay, respectively." (PMID 23294544, 2013). "Additionally, all utility values of the newly tested parameters (CXCL5, CXCL14) were greater than those obtained for CA 19–9, which suggests their higher utility than this routine marker for colorectal cancer patients." (PMID 37848726, 2023). "In addition, the invasion ability of cancer cells was also regulated by CXCL14 expression, which suggests the pathogenicity of CXCL14 in colorectal cancer." (PMID 38075694, 2023). "However, the opposite results have also been reported, for example, elevated CXCL14 expression in tumor specimens of stage III/IV correlated with worse OS in colorectal carcinoma." (PMID 36012586, 2022). "CXCL14 is another potential tumor inhibiting gene in colorectal carcinoma and downregulation of this gene may result in a more aggressive phenotype of colorectal cancer." (PMID 32523911, 2020). "To investigate the potential clinical role of chemokine CXCL14 in colorectal cancer, immunohistochemistry staining was performed on 265 colorectal cancer specimens and 129 matched adjacent normal colorectal mucosa specimens with an antibody to CXCL14, the specificity of which we first confirmed." (PMID 23294544, 2013). "The underlying mechanisms of CXCL14-enhanced colorectal cancer cell migration and invasion are not clear." (PMID 23294544, 2013). "Furthermore, in early stage I colorectal cancer, CXCL14 expression was up-regulated compared with adjacent normal mucosa, suggesting that CXCL14 over-expression is an early event in the development of CRC." (PMID 23294544, 2013). "These analyses suggested that up-regulation of CXCL14 might be involved in colorectal cancer initiation and progression." (PMID 23294544, 2013).